FH (fumarate hydratase)
Diseases named in the same sentence as FH in open-access papers (continued):
Sharing a sentence is not in itself a finding about the gene and the disease.
cancer (continued). "Having analyzed the prevalence of pathogenic/likely pathogenic germline variants in cancer-predisposition genes in 334 HCC patients considered for liver transplantation, we found only 7/334 (2.1%) carriers of pathogenic variants in established cancer-predisposition genes (PMS2, 4×NBN, FH or RET)." (PMID 36612198, 2022). "However, cells can proliferate without this enzyme, and, moreover, mutation or deletion of FH is an apparent driver of various cancers." (PMID 36428601, 2022). "To the best of our knowledge, this study is the first to elucidate the mechanisms that underlie the anti-cancer properties of MSPA, which we reveal were mediated through the simultaneous suppression of key enzymes in glycolysis and the tricarboxylic acid cycle, namely ALDOA, ENO1, and FH." (PMID 34681284, 2021). "Patients with pathogenic mutations in SDHB and FH, for example, have an elevated risk for malignant tumor development, regardless of whether the mutation was inherited or whether it occurred somatically." (PMID 31212687, 2019). "There is a renewed interest in the area of cancer metabolism with metabolic reprogramming coined as a hallmark of cancer based on the discovery of mutations and alterations in IDH1 and IDH2 along with succinate dehydrogenase (SDH), fumarate hydratase (FH), and pyruvate kinase M2 (PKM2)." (PMID 30024920, 2018). "Furthermore certain types of cancer have been associated with some Tricarboxylic Acid Cycle (TCA) enzymes mutations, including isocitrate dehydrogenase (IDH1 and IDH2), succinate dehydrogenase (SDH) and fumarate hydratase (FH)." (PMID 27029038, 2016). "Moreover, cancer-associated mutations have been identified in gene encoding for several metabolic enzymes such as succinate dehydrogenase (SDH), fumarate hydratase (FH), and isocitrate dehydrogenase (IDH), all enzymes of the tricarboxylic acid cycle (TCA cycle) in mitochondria." (PMID 27023612, 2016). "Furthermore, cancer associated mutations have been identified in genes of known metabolic function; namely isocitrate dehydrogenase 1 and 2 (IDH1 and 2), succinate dehydrogenase (SDH) and fumarate hydratase (FH; Semenza, 2011)." (PMID 22866264, 2012). "In cancer cells harboring mutant IDH1, SDH, or FH, excess oncometabolites (such as D-2-HG, succinate, or fumarate) accumulate, inhibiting PHD and FIH activity, thereby driving cancer progression and therapy resistance." (PMID 40487432, 2025). "In order to investigate the effect of FH expression on cancer cells, we first checked the expression of FH in various CRC cell lines to choose the optimal cell lines used for silencing and overexpression of FH." (PMID 38398104, 2024). "Mutation/activity loss of isocitric acid dehydrogenase (IDH), succinate dehydrogenase (SDH), and fumarate hydratase (FH) in the tricarboxylic acid cycle leads to TCA circulatory dysfunction and mitochondrial metabolic defects in many cancers." (PMID 38288377, 2024). "To further analyze the important roles of TOMM40 and FH in other malignancies, we performed a pan-cancer analysis of TOMM40 and FH." (PMID 38285218, 2024). "Mutations in Krebs cycle enzymes, such as succinate dehydrogenase (SDH), fumarate hydratase (FH), and isocitrate dehydrogenase (IDH), contribute to cancer progression." (PMID 39456607, 2024). "Similarly, in the CML cell line K562, HIF-1α could strengthen the invasiveness of cancer cells by elevating the level of glycolysis in response to the knockdown of fumarate hydratase (FH) expression, while also entailing a reduced ability to repair DNA after damage." (PMID 37588219, 2024). "Since biallelic FH inactivation is exclusive to cancer cells in HLRCC patients, the biological alterations driven by FH inactivation present unique opportunities for targeted therapy." (PMID 38793008, 2024).
cancer (continued). "Mutations in the TCA enzymes, such as succinate dehydrogenase (SDH), fumarate hydratase (FH), and isocitrate dehydrogenase (IDH), have been reported in different cancers and are also responsible for the induction of aerobic glycolysis." (PMID 37445598, 2023). "Hypoxia-inducible factor 1α (HIF1α), whose overexpression occurs in many cancers as an adaptive regulator of hypoxia for tumorigenesis, is stabilized by defects in metabolic enzymes such as succinate dehydrogenase (SDH) and fumarate hydratase (FH)." (PMID 36609747, 2023). "Therefore, cancer cells may depend equally or predominantly on OXPHOS for ATP supply, with the exemption of tumors with mutations in the tricarboxylic acid (TCA) cycle enzyme genes SDH, IDH, and FH, important during mitochondrial respiration." (PMID 35831624, 2022). "Based on function, the 12 FRGs can be grouped into four classes: Lipid metabolism (GPX4, LPCAT3, ACSL5, and ACSL6), antioxidant metabolism (CD44, SESN2, and AIFM2), iron metabolism (CISD1 and HSPB1), and cancer metabolism (SOCS1, FH, and G3BP1)." (PMID 34784264, 2022). "The 12 FRGs are divided into 4 categories according to their functions: lipid metabolism (GPX4, LPCAT3, ACSL5, ACSL6), antioxidant (CD44, SESN2, AIFM2), iron metabolism (CISD1, HSPB1), and cancer metabolism (SOCS1, FH, G3BP1)." (PMID 35559049, 2022). "In several types of cancer including breast, enzymes that participate in TCA such as isocitrate dehydrogenase (IDH), succinate dehydrogenase (SDH), and fumarate hydratase (FH) are deregulated, affecting enzymes involved in epigenetic processes." (PMID 34692471, 2021). "We found that in some cancers, especially in LUAD and TGCT, FH expression was significantly correlated with multiple immune checkpoint markers, such as BTLA, TNFRSF14, LAIR1, CD48, and CD28." (PMID 34737838, 2021). "However, the role of FH in human different cancers remains unknown." (PMID 34737838, 2021). "These groups were used to test the family-wide significance of changes in expression (mRNA or protein), CNA and mutation of each group in three local cancer (MSKCC, PRAD, OICR) and four advanced (MICH, FH, NEURO and SU2C) cancer cohorts." (PMID 33230156, 2020). "The genes of fumarate hydratase (FH) and succinate dehydrogenase (SDH) aremutated in many cancer types." (PMID 33456974, 2020). "Some metabolic enzymes, such as succinate dehydrogenase (SDH), fumarate hydratase (FH), IDH and pyruvate kinase 2 (PKM2) are likely to activate HIF-1 pathway by stabilizing HIF-1α, therefore enhancing cancer metastasis." (PMID 33489906, 2020). "FOXO3a activation decreases total oxygen consumption in cancer cells because PDK4 is upregulated, and several genes of the Krebs cycle (FH) and OxPhos (ND1, COX) are downregulated." (PMID 31600993, 2019). "Enzymes that have been formerly related to cancer are suggested within the TCA cycle, like “fumarate hydratase”, “succinate dehydrogenase” and “aconitase”." (PMID 30577788, 2018). "In this study, combined effects of FH (E404D) and ACOX2 (R409H) on metabolic switch from fatty acids to glucose were remarkably distinct, which might be an essential precondition to trigger the occurrence of PMCTs and mimic the Warburg effect, a hallmark of cancer metabolism." (PMID 30062063, 2018). "Alterations in TCA cycle metabolites in cancer cells are largely attributed to disruptions in cycle integrity, particularly at the levels of isocitrate dehydrogenase (IDH), succinate dehydrogenase (SDH), and fumarate hydratase (FH)." (PMID 41154474, 2025). "Furthermore, fumarate hydratase (FH), an enzyme that converts fumarate into malate in the TCA cycle, makes cancers more sensitive to ferroptosis induced by cystine depletion." (PMID 38459004, 2024). "The upregulation of FH and MDH2 is higher in HPDE than in SW1990 cells, which may be related to the enhanced anaerobic glycolysis phenotype in cancer cells." (PMID 38483955, 2024).
cancer (continued). "The complete absence of FH immunohistochemical staining in the cytoplasm of the cancer cells is helpful for the diagnosis of FH-RCC." (PMID 39555225, 2024). "Our results showed that the expression of FH and MDH2 were generally upregulated in cancer cells." (PMID 38483955, 2024). "We also performed the co-expression analysis of TOMM40 and FH with immune-related cells, and TOMM40 and FH could affect immune cell infiltration in pan-cancer." (PMID 38285218, 2024). "The variants we found in non-syndromic patients (FH, PTEN) are usually identified in patients with syndromic forms of cancer, which was not the case in our study." (PMID 38002934, 2023). "In addition, as we know, fumarate hydratase (FH) is an enzyme in the TCA cycle that catalyzes the transformation of fumarate into malate and has the function of suppressing cancer and the DNA damage response pathway (DDR)." (PMID 37325669, 2023). "In accordance with this, many dysregulations of SDH, FH, and α-KGDH are described in cancer." (PMID 35178152, 2022). "In summary, MSPA exhibits anti-cancer effects by simultaneously targeting ENO1, ALDOA, and FH." (PMID 34681284, 2021). "Furthermore, various mutations in Krebs cycle enzymes, including succinate dehydrogenase (SDH), fumarate hydratase (FH), and isocitrate dehydrogenase 1 (IDH1) and 2 (IDH2), are described in cancer cells." (PMID 34445360, 2021). "MSPA also inhibited cancer cell proliferation and induced apoptosis by inhibiting critical enzymes involved in the Warburg effect: aldolase A (ALDOA), enolase 1 (ENO1), and fumarate hydratase (FH)." (PMID 34681284, 2021). "Our studies also show an analogous induction of UPR and HBP, but in the surprising context of Asn exposure of cancer cells lacking FH activity." (PMID 32774853, 2020). "CDH1, FH, and CDKN1B are all involved in pathways in cancer." (PMID 29738475, 2018). "The flexible functional role of FH reflected here is attributed to the counteractive effect of OGT activity on AMPK signaling; this finding would valuably provide new molecular basis for developing effective cancer therapy in future." (PMID 31225435, 2017). "MDH2 has not been a popular cancer-related target of interest, unlike fumarate hydratase (FH), succinate dehydrogenase (SDH) and isocitrate dehydrogenase (IDH)." (PMID 27611801, 2016). "Given the induction of a pseudohypoxic response that can be reversed by re-expressing SDHA and FH, we asked whether ARRB1 might have broader effects on cancer cell metabolism." (PMID 24837709, 2014). "The absence of FH and subsequent accumulation of fumarate lead to epithelial-to-mesenchymal transition (EMT), a phenotypic transition associated with the initiation, invasion, and metastasis of cancer." (PMID 38139831, 2023). "Although the activity of mFAO has not been studied in cancer cells containing simultaneously mutations in the Krebs cycle, it is worth asking: how can mFAO work with a disrupted Krebs cycle due to mutations in SDH, FH, and/or a-KGDH?" (PMID 35205619, 2022). "Although it is now clear that most cancer cells do not have a defect in mitochondrial metabolism, rare mutations in the TCA enzymes succinate dehydrogenase and fumarate hydratase have been shown to force a switch to Warburg metabolism and contribute to inherited and sporadic cancers." (PMID 32213952, 2020). "We have demonstrated that both strategies hamper cancer cell viability and self-renewal capacity and confirmed that the concept of synthetically lethal interactions of HMOX1 and FH genes might be an attractive option for the treatment of HLRCC-associated tumors." (PMID 31963199, 2020).
cancer (continued). "Thus, metabolic disorder due to mutations in metabolic genes, such as isocitrate dehydrogenase, fumarate hydratase, and succinate dehydrogenase, could reduce TET enzymatic activity, leading to the impairment of DNA hydroxymethylation, and could contribute to cancer progression." (PMID 34731191, 2021). "More than 200 distinct variants spread over the entire coding region of the FH gene have been published in the Leiden Open (source) Variation Database system (LOVD) and so far, a clear correlation between the type or location of the FH mutation and cancer risk has not been observed." (PMID 31792767, 2020). "The altered metabolic phenotype of cancer usually does not result from mutations in specific metabolic genes, except for rare mutations in two enzymes of the TCA, succinate dehydrogenase (SDH) and fumarate hydratase (FH), but rather is the result of mutations in metabolic regulators." (PMID 26339588, 2015). "According to results, FH and CA I were the two proteins that decreased in cancer tissues with PVT, but not in the cancer tissues without PVT." (PMID 28785178, 2017). "Western blotting of carbonic anhydrase I (CA I), fumarate hydratase (FH), and betaine–homocysteine S-methyltransferase 1 (BHMT) were performed and definitely showed they were down-regulated in the cancer tissues of HCC with PVT, compared to HCC without PVT." (PMID 28785178, 2017). "But, when we focused on the protein expression with fold-difference to adjacent noncancerous tissue or cancer tissue without PVT forming, FH, CA I, BHMT, IVD, CRAT, and arginase-1 were the six proteins which expressed deficiently in cancer cells with PVT." (PMID 28785178, 2017). "Although not the case for all cancers, RCC has been regarded as a cancer driven by metabolic disorders due to the abnormal expression of genes that regulate various metabolic pathways, such as FH and SDHB in the Krebs cycle (Linehan, Srinivasan & Schmidt, 2010)." (PMID 32832275, 2020).
infection (10 papers, 2012 to 2024). The state of being infected such as from the introduction of a foreign agent such as serum, vaccine, antigenic substance or organism. "Two weeks after infection, 2 out of 5 mouse serum proteins were upregulated (mouse complement factor H [FH] and UDP-N-acetylhexosamine pyrophosphorylase)." (PMID 35271623, 2022). "In the TCA cycle, six of eight metabolic fluxes were significantly increased at 4 h post-infection compared to 2 h post-infection, while the flux through fumarate hydratase was significantly decreased." (PMID 33207684, 2020). "Previous studies on PspC and on fH and sIgA have also shown the role of these interactions in promoting immune evasion and epithelial adhesion during infection with S. pneumoniae." (PMID 29535198, 2018). "On infection with adenoviral vector expressing Cre recombinase (Ad-Cre), Fh1fl/fl cells, which lost FH activity, underwent proliferation arrest, whereas the uninfected cells continued to proliferate." (PMID 25613188, 2015). "Interestingly, for the H1N1 IAV strain, we observed an enhancement of the amount of viral protein in the cells at 8 hours post infection when the H1N1 virus was pre-incubated with FH protein." (PMID 38698856, 2024). "We hypothesized that binding of HA protein to human FH may affect the entry process of IAV during infection of target cells." (PMID 38698856, 2024). "Furthermore, a few studies have demonstrated that the fH/sIgA binding regions on PspC are targets for anti-PspC antibodies during infection and that these anti-PspC antibodies have the capacity to impede the interaction between PspC and fH/sIgA." (PMID 29535198, 2018). "Since FHR1 helps to combat infection by out competing FH at the bacterial surface, it makes some sense to see an apparent increased representation of those individuals in a secondary aHUS cohort, i.e. the CFHR3-CFHR1 deletion is not only associated with increased risk of FH autoantibody." (PMID 38274833, 2023). "At 4 hours post infection, we found that both human H1N1 (A/England/195/09) and H3N2 (A/Hong Kong/1774) IAV that were preincubated with FH prior to infection showed reduced entry to A549 cells by both immune-staining and western blot analysis compared to IAV that were not pre-incubated with FH." (PMID 38698856, 2024). "To assess whether the interaction between FH and IAV HA affects life cycle functions of the virus, we carried out infection assays where IAVs were preincubated with FH before being allowed to infect a human pneumocyte cell line, A549." (PMID 38698856, 2024). "Host restrictions in two soluble negative regulators of the complement cascade, factor H (fH) and C4b-binding protein (C4BP), also exist and are especially important to consider when testing vaccines that clear Ng infection through bactericidal and opsonophagocytic activity." (PMID 33290434, 2020). "There is no information on the function of FH in Trichinella infection; however, increasing FH concentration during the early stages of infection may protect larvae against complement killing while traveling through the bloodstream prior to infecting striated muscle." (PMID 35271623, 2022).
metabolic disorder (9 papers, 2016 to 2025). "Fumarate hydratase (FH) deficiency is a rare, yet impactful metabolic disorder caused by mutations in the FH gene, affecting the Krebs cycle, leading to the accumulation of fumarate and pseudohypoxic states." (PMID 40002168, 2025). "Fumarate hydratase (FH) deficiency is a rare metabolic disorder that disrupts the normal function of the citric acid cycle, an essential pathway for cellular energy production." (PMID 40002168, 2025). "The inhibition of TET-dependent DNA demethylation may result from either a deficiency of cofactors or the accumulation of 2-hydroxyglutarate, succinate and fumarate in the cell due to a metabolic disorder or mutations (for example, in the fumarate hydratase gene FH)." (PMID 36982825, 2023). "As a metabolic disease, many mutated genes, such as VHL, fumarate hydratase (FH), and succinate dehydrogenase (SDH), are involved in cellular respiration and energy metabolism." (PMID 32461965, 2020). "Collectively, our results indicate the potential value of this FH+/− KO rat model in the studies of metabolic disorders and tumorigenesis in vivo." (PMID 27556703, 2016). "ccRCC has been considered a type of metabolic disease on the basis of the upregulation of several gene products e.g., VHL, MET, fumarate hydratase (FH), folliculin (FLCN), succinate dehydrogenase (SDH) and, TSC1/2 that regulate the mTOR pathway, PTEN, and other energy metabolism-related pathways." (PMID 33920158, 2021).
genetic disorder (6 papers, 2020 to 2025). "However, those with a pathogenic FH mutation causing high LDL-C levels align with the classical concept of FH as a monogenic autosomal genetic disease." (PMID 36561318, 2022).
renal diseases (5 papers, 2012 to 2025). "Specific mutations and variants in the FH gene are associated with broad range of phenotypes, from early onset renal diseases with high mortality rates to disorders limited to the eye." (PMID 24338037, 2014). "The FH mutation in this case was thought to have been inherited from the patient’s mother because there was a high incidence of UL on the maternal side and because the patient’s maternal aunts also had kidney disease." (PMID 39184870, 2024). "In the in vivo studies, U concentrations of P, fH and membrane attack complex (MAC) were measured in patients with renal diseases using an enzyme-linked immunosorbent assay (ELISA), and their relationships with the clinical data were evaluated." (PMID 24885016, 2014). "In the context of renal disease, this study represents the first analysis, as per our knowledge, to clarify the role of AP regulation by measuring the combination of U-P, fH and MAC in the same samples from patients with various renal diseases." (PMID 24885016, 2014). "First, we demonstrated that U-P, fH and MAC levels were significantly higher in patients with various renal diseases than in healthy controls and were correlated with U-protein levels and tubular damage markers." (PMID 24885016, 2014). "In the in vivo studies, we measured the U-complement components (P, fH and MAC) in patients with various renal diseases and examined their relationships with the clinical data." (PMID 24885016, 2014).